KIR3DL1 (killer cell immunoglobulin like receptor, three Ig domains and long cytoplasmic tail 1)
Diseases named in the same sentence as KIR3DL1 in open-access papers (continued):
Sharing a sentence is not in itself a finding about the gene and the disease.
viral infection (13 papers, 2012 to 2025). "Consistent with our findings, the coinheritance of inhibitory KIR3DL1 and its cognate ligand HLA-Bw4 is associated with clearance of several viral infections, including conferring protection against influenza A (H1N1/09) virus infection." (PMID 35273641, 2022). "Also, HLA-B*27:05 in complex with other peptides leads to incapacity of KIR3DL1 to recognize this allele, and the result is increased activation of NK cells during viral infection." (PMID 39201523, 2024). "Furthermore, certain HLA/KIR genotype combinations have been associated with a control of viral infection, such as the KIR3DL1*h/*y and HLA-B*57 being more frequently found in HESN than HIV-infected individuals." (PMID 33803543, 2021). "KIR3DL1-HLA class I interactions influence immune responses in a range of settings, including hematopoietic cell transplantation, viral infection, cancer immunotherapy, and even neurological disease." (PMID 40609790, 2025). "Altogether, the KIR3DL1+HLA-Bw4+ combination protects an array of viral infections, including SARS-CoV2, H1N1/09, HIV, and human papillomavirus." (PMID 35273641, 2022). "The stronger inhibitory interactions conferred by KIR3DL1 during NK cell development can lead to a stronger NK cell reaction when the ligand is downregulated during viral infection." (PMID 36555106, 2022). "KIR3DL1 is a protein coding gene and is a inhibitory receptor that binds to groups of HLA-A and HLA-B allotypes, which plays an important role in viral infections, cancers, autoimmunity, and transplantation." (PMID 34738870, 2021). "In seronegative individuals exposed to HIV infection it would seem that the reduced frequency of KIR3DL1 and its HLA-Bw4 ligand offers protection against this viral infection by increasing NK cell activation." (PMID 26744892, 2016). "We next tested if training KIR3DL1+ NK cells with a Bw4+BCL could enhance their response to target cells that had lost HLA expression due to a viral infection." (PMID 31723004, 2019). "However, the down‐regulation of major histocompatibility complex (MHC) class I molecules that often follows viral infection or cellular transformation alleviates NK cell inhibition via KIR3DL1, leading to proinflammatory cytokine release and cytolytic activity." (PMID 26439909, 2016). "Strong inhibitory KIR3DL1 ligation has been demonstrated to improve NK cell activation and antibody-dependent cellular cytotoxicity (ADCC), inhibit HIV-1 replication in autologous infected CD4+ T cells, and enhance survival of CD8+ T cells in viral infection." (PMID 35235807, 2022).
acute myeloid leukemia (8 papers, 2019 to 2024). Acute myeloid leukemia (AML) is a group of neoplasms arising from precursor cells committed to the myeloid cell-line differentiation. "KIR3DL1*004 is also reported to be protective against relapse in patients with acute myeloid leukemia (AML) after HLA-matched HSCT and against HIV disease progression, which emphasizes the underlying and intriguing function of this frequent null KIR3DL1 allele in Caucasians." (PMID 37345091, 2023).
neuroblastoma (8 papers, 2017 to 2025). Neuroblastoma (NB) is the most common solid, extracranial childhood tumor. "We have previously shown that this interaction of inhibitory KIR2DL2 and KIR3DL1 with their ligands was associated with improved outcome in follicular lymphoma and neuroblastoma patients receiving rituximab maintenance therapy and dinutuximab monoclonal antibody (mAb) immunotherapy, respectively." (PMID 36823323, 2023). "A recent study observed that the inhibitory genes KIR2DL1 and KIR3DL1 had high frequencies in patients with neuroblastoma." (PMID 40244151, 2025). "In a study of neuroblastoma patients mentioned previously, we found that patients that had both KIR2DL2+/C1+ [KIR2DL2+ and HLA-C1+ (C1/C1 or C1/C2)] and KIR3DL1+/Bw4+ (i.e. Group 1) had improved clinical outcome if treated with monoclonal antibody-based immunotherapy compared to no-immunotherapy." (PMID 30871628, 2019). "For example, compared to donor NK cells with strong KIR3DL1 binding HLA allotypes, donor NK cells expressing KIR3DL1 with weak or no binding to HLA-B allotypes were associated with improved control for AML patients and for neuroblastoma patients receiving anti-GD2 Ab therapy." (PMID 30626155, 2019). "Similar to the trends for improved EFS observed in neuroblastoma patients treated with immunotherapy, those FL patients who were not KIR3DL1+/B-Bw4-I80+ had improved duration of response if treated with maintenance rituximab as compared to no-maintenance (p = 0.002)." (PMID 28659916, 2017). "In both clinical trials, patients with KIR3DL1+/A-Bw4+ or with KIR3DL1+/B-Bw4-T80+ genotypes randomized to neuroblastoma immunotherapy or FL maintenance immunotherapy had better outcome versus those randomized to no immunotherapy for neuroblastoma or non-maintenance for FL." (PMID 30871628, 2019).
ankylosing spondylitis (6 papers, 2006 to 2022). An autoimmune chronic inflammatory disorder characterized by inflammation in the vertebral joints of the spine and sacroiliac joints. "Besides, there are previous studies in other class-I pathologies such as psoriatic disease (PD) and ankylosing spondylitis (AS), in which a protective association of the KIR3DL1*004 allele has been reported." (PMID 31849952, 2019). "In our study, we have not seen any association of KIR3DL1, putative receptor of HLA-B27, and only weak association of KIR3DS1, with ankylosing spondylitis (data not shown)." (PMID 20865034, 2010).
malaria (6 papers, 2012 to 2025). Malaria is a serious and sometimes fatal disease caused by a parasite that commonly infects a certain type of mosquito which feeds on humans. "Additionally, KIR3DL1 has been positively associated with malaria severity." (PMID 40244151, 2025). "Interestingly, malaria-exposed children and eBL patients express the KIR3DL1*High phenotype, a proposed mechanism by which malaria subverts NK-cell mediated immune responses." (PMID 37647275, 2023). "Another small-scale field-based study conducted in no-pregnant adults in Solomon Island (n = 77) found that malaria positive individuals had a high frequency of KIR3DL1/KIR3DS1 heterozygosity in combination with non-deleted KIR2DS4 allelic variant." (PMID 22715396, 2012).
hepatocellular carcinoma (5 papers, 2011 to 2021). A malignant tumor that arises from hepatocytes. "The compound genotype KIR3DS1/Bw4-80I that favours NK cell activation is associated with chronic HCV carriage in people with hepatocellular carcinoma and inactivating KIR3DL1 is associated with spontaneous HCV clearance." (PMID 29149205, 2017). "HLA-Bw4 and the KIR3DL1+HLA-Bw4 pair were significantly associated with hepatocellular carcinoma onset during a median follow-up of 6.6 years, which suggested that functional interactions between KIR and HLA or HLA-Bw4 may influence the risk of cancer development." (PMID 34209910, 2021).
leukemia (5 papers, 2016 to 2024). A malignant (clonal) hematologic disorder, involving hematopoietic stem cells and characterized by the presence of primitive or atypical myeloid or lymphoid cells in the bone marrow and the blood. "That is, the high frequency of inhibitory KIR2DL1, KIR2DL2 and KIR3DL1 strongly suppresses NK cell function, thus increasing the risk of developing leukaemia." (PMID 38527290, 2024). "Additionally, the results highlighted a negative correlation between the pathogenesis of leukemia and KIR3DL1, KIR3DS1, KIR2DL1, and KIR2DL5 genes, a very suggestive finding that KIR polymorphisms are associated with susceptibility to leukemia in Hans." (PMID 27708784, 2016). "However, further investigations are needed to evaluate the role of other inhibitory KIR receptors, such as KIR2DL1, KIR3DL1 and KIR3DL2, in anti-leukemia NK cell responses, particularly against AML." (PMID 32708751, 2020). "Interestingly, we also saw different behaviors of KIR3DL1 expression in myeloid and lymphoid leukemias, but there was no leukemic blast infiltration during the first three months, suggesting the influence of pre-transplant treatment, rather than the type of leukemia." (PMID 33138211, 2020).
Autoimmunity (4 papers, 2016 to 2023). The occurrence of an immune reaction against the organism's own cells or tissues. "Due to their established associations with multiple human ailments including infectious disease, cancer and autoimmunity, we focused this study on determining the allotypes of KIR3DL1/S1." (PMID 35192601, 2022). "Yet, the absence of KIR3DS1 in the presence of its inhibitor homologue, KIR3DL1, was indicative of the inhibitory or protective role played by NK cells, which perhaps avoids subsequent immune responses that may trigger inflammation and autoimmunity." (PMID 27827450, 2016).
melanoma (4 papers, 2019 to 2022). A malignant, usually aggressive tumor composed of atypical, neoplastic melanocytes. "In consistency with this study, the combination of KIR3DL1 with less effective Bw4T80 has been reported in primary melanoma patients compared to metastatic patients, since KIR3DL1 generates a weaker inhibitory signal when an threonine residue is present at position 80 (Bw4T80)." (PMID 31103021, 2019). "In one study, KIR3DL1 and KIR2DL3 were expressed at higher levels on the NK cells of melanoma patients, while other studies found an increase in KIR2DL1 and KIR2DL2/2DL3." (PMID 33802954, 2021). "On the other hand, the expression levels of inhibitory receptors on NK cells were increased: for example, KIR3DL1 in PT-2, GC, and CRC; KIR2DL2/L3 in melanoma; NKG2A in BT, LT, and CRC; PD-1 in ET, HCC, CRC, GC, biliary tumor, and LT; TIM-3 in LT, melanomas, and GC." (PMID 36560427, 2022).
psoriasis (4 papers, 2020 to 2024). An autoimmune condition characterized by red, well-delineated plaques with silvery scales that are usually on the extensor surfaces and scalp. "KIR proteins are believed to play an important role in regulating the NK immune response and, particularly KIR3DL1 has been found associated to psoriasis inflammation." (PMID 38601151, 2024). "In a previous small-scale study, we showed that the low and null allotypes of KIR3DL1 are associated with increased and decreased risk for psoriasis, respectively." (PMID 34177931, 2021). "We also showed that KIR3DL1 low in combination with HLA-Bw4 significantly increases risk for psoriasis." (PMID 34177931, 2021). "The epitope is associated with psoriasis, where KIR3DS1/HLA-A-Bw4 genotype was positively associated with disease susceptibility and KIR3DL1/HLA-B-Bw4-80I was negatively associated." (PMID 34943866, 2021). "KIR genes, including KIR2DS1, KIR3DL1, and KIR3DS1 have previously been implicated in psoriasis susceptibility." (PMID 34177931, 2021). "According to our results, we could hypothesize that the receptors KIR3DS1 and KIR3DL1 could modulate the development of psoriasis through binding to their ligands in two aspects." (PMID 32235781, 2020).
uveitis (4 papers, 2014 to 2021). An inflammatory process affecting a part of or the entire uvea. "Evaluated by absence or presence of 16 KIR genes, KIR3DL1-/2DS3- was significantly associated with increased risk of uveitis in patients with AS." (PMID 33912164, 2021). "KIR3DL1 expressing NKB1+CD56+ NK cells were increased among BD patients with uveitis while the expression of the other NK receptors such as CD94 and CD158b remained unchanged in the CD56+ NK cells of BD patients." (PMID 33717125, 2021). "The presence of KIR3DL1 is protective for AS, particularly AS with uveitis (UV)." (PMID 24988487, 2014).
autoimmune hepatitis (3 papers, 2021 to 2022). Hepatitis caused by autoantibodies. "KIR–HLA pairs might influence disease progression as well; in our recent examination of KIR–HLA pairs in patients with autoimmune hepatitis, KIR3DL1+HLA-Bw4 was significantly related to a favorable outcome." (PMID 34209910, 2021).
chronic hepatitis C (3 papers, 2013 to 2018). "This study revealed that patients with chronic hepatitis C had a significantly higher incidence rate of KIR3DL1-HLA-Bw4 pairs." (PMID 29731972, 2018). "Frequency of IL28B genotype, KIR3DL1/HLA-Bw4, and KIR2DL2/HLA-C1 combinations in 56 patients with a sustained virological response (SVR) and 59 patients with a non-SVR to pegylated interferon and ribavirin therapy of chronic hepatitis C." (PMID 24349500, 2013).
Cirrhosis (3 papers, 2017 to 2025). A chronic disorder of the liver in which liver tissue becomes scarred and is partially replaced by regenerative nodules and fibrotic tissue resulting in loss of liver function. "Since KIR3DL1 positivity was 94.7% in HCV-associated cirrhosis in our cohort, it was difficult to conclusively ascertain HLA-Bw4 or KIR3DL1 + HLA-Bw4 as risk factors for HCC development." (PMID 34209910, 2021). "In the group of individuals with a shorter infection time who developed cirrhosis, we detected decreased expression of KIR3DL1 in CD56dim NK cells in the presence of its ligand." (PMID 29354127, 2017). "Additionally, in individuals with a shorter duration of infection who progressed to cirrhosis, a reduction in the expression of KIR3DL1 was observed." (PMID 40244151, 2025). "Thus, we postulated that lower KIR3DL1 expression during early infection or NKG2A expression during late infection may contribute to progression to cirrhosis." (PMID 29354127, 2017). "Additionally, KIR3DL1/HLA-B Bw4 and KIR3DL1/HLA-B Bw4-80Ile are protective against liver decompensation and related deaths, while the absence of KIR3DL1/HLA-B Bw4 and the presence of cirrhosis at diagnosis are associated with disease progression." (PMID 40244151, 2025). "Furthermore, KIR3DL1 expression was also decreased in peripheral blood CD56dim NK cells (together with its Bw4 ligand) from the group of early-infected patients who developed cirrhosis (5 vs. 32% in patients without cirrhosis, p = 0.03)." (PMID 29354127, 2017).
Diabetes (3 papers, 2022 to 2025). "Collectively, these results suggest that KIR3DL1 and KIR2DS4 as well as KIR2DL3 can be associated with diabetes and hypertension, respectively, among people living and aging with HIV." (PMID 35071606, 2022).
HCMV infection (3 papers, 2018 to 2025). "Furthermore, these NK cells often also express KIR3DL1 or KIR3DS1, regardless of the presence of HLA-Bw4, suggesting a potential role of these receptors in the control of CMV infection." (PMID 40244151, 2025).
influenza (3 papers, 2014 to 2025). An acute viral infection of the respiratory tract, occurring in isolated cases, in epidemics, or in pandemics; it is caused by serologically different strains of viruses (influenzaviruses) designated A, B, and C, has a 3-day incubation period, and usually lasts for 3 to 10 days. "However, an analysis of intensive care unit patients showed fewer deaths from influenza (H1N1) among KIR3DL1/S1+ patients compared to KIR3DL1/S1− patients." (PMID 41573579, 2025). "NK cell response related genes such as CD247, KIR2DL4, KIR3DL1, KIR3DL3 and KLRB1 were down-regulated only in moderate and severe patients while genes such as KIR2DL1, KIR2DS4 and KIR3DL2 were down-regulated in all three groups of influenza patients." (PMID 25365328, 2014). "A more complex picture was observed in a clinical study in which either KIR3DL1/S1- or KIR2DL1-expressing individuals lacking the ligand or KIR2DL2/L3 and its cognate ligand were enriched among ICU patients during the 2009 influenza pandemic." (PMID 27635417, 2016).
multiple sclerosis (3 papers, 2021 to 2023). A progressive autoimmune disorder affecting the central nervous system resulting in demyelination. "The KIR3DL1 has been linked to several aspects of natural killer cell responses, which in turn have been linked to susceptibility to multiple sclerosis, especially in African-Americans57." (PMID 34702870, 2021).
Sepsis (3 papers, 2012 to 2025). Sepsis is defined as life-threatening organ dysfunction caused by a dysregulated host response to infection. "The frequency of KIR3DL1+ in the AC patients significantly increased the mortality from sepsis (p = 0.045), which was confirmed by multivariate logistic regression." (PMID 37046435, 2023). "The frequency of KIR3DL1+ in the AC patients significantly increased the mortality from sepsis (p = 0.012) and was confirmed by multivariate logistic regression." (PMID 37046435, 2023). "Only the inhibitor gene KIR3DL1+ showed statistically significant differences and was significantly higher in AC patients without encephalopathy or death from GF than sepsis or MF (97%, 68%, and 74%, p = 0.045)." (PMID 37046435, 2023). "Interestingly, the only significant difference observed was a higher proportion of NK cells expressing the inhibitory receptor KIR3DL1 in patients with Sepsis compared to non-septic SIRS." (PMID 23236375, 2012).
acute GVHD (2 papers, 2022 to 2025). "A predictive model using five of such polymorphisms (CXCL12 rs2839695, IL12A rs7615589, KIR3DL1 rs4554639, TGFB2 rs5781034 for the recipient and CD48 rs2295615 for the donor) together with the development of acute GVHD grade III/IV improved risk stratification of CMV reactivation." (PMID 35525883, 2022).
Behçet disease (2 papers, 2019 to 2020). "We recently showed that high-expressing allotypes of KIR3DL1, including 3DL1*001, can protect from Behçet disease." (PMID 32300348, 2020).
cervical cancer (2 papers, 2019 to 2024). A primary or metastatic malignant neoplasm involving the cervix. "KIR3DL1 could serve as a relevant marker for immunosurveillance in cervical cancer cells.The immune responses of IDO2 and B cells are closely related." (PMID 39720726, 2024). "Furthermore, we found that some cervical cancer cells expressed typical markers of NK cells like NKp30, NKp46, NKG2A, and KIR3DL1." (PMID 31198791, 2019).
endometriosis (2 papers, 2022 to 2023). The growth of functional endometrial tissue in anatomic sites outside the uterine body. "KIR2DL4 and KIR3DL1 are members of the killer cell immunoglobulin-like receptor family and might be associated with the pathogenesis of endometriosis through their involvement in the regulation of NK cell activity." (PMID 37662927, 2023).
hepatitis C virus infection (2 papers, 2021 to 2026). A viral infection caused by the hepatitis C virus. "For example, CNV of KIR3DL1/S1 influences HIV control and expression differences of KIR2DL3, interacting with HLA-C, may have a profound effect on resolution of hepatitis C virus infection." (PMID 33632228, 2021).
lung carcinoma (2 papers, 2022 to 2023). "We couldn’t detect a significant association of 2DS1/C2, 3DS1/Bw4 combinations with lung cancer, though the HLA-Bw4 (Ile80) allele and KIR3DL1/Bw4 were strongly associated with protection against lung cancer." (PMID 36241658, 2022).
pancreatic cancer (2 papers, 2013 to 2014). "However, there was no significant change in the percentages of NK cells positive for activating surface receptors (NKp44 and NKp80) or inhibitory surface receptors (KIR3DL1 and KIR2DL1/DS1) with either of the pancreatic cancer cell lines." (PMID 25274283, 2014). "Two inhibitory surface receptors, KIR3DL1 and KIR2DL1/DS1, were investigated in this study, however we found no significant alteration in their expression in NK cells that following exposure to pancreatic cancer cells." (PMID 25274283, 2014).
VKH disease (2 papers, 2016). "Four of the six HLA class I molecules that displayed negative association with VKH disease function as ligands for KIR receptors–HLA-B44 and B52 carry the Bw4 ligand that binds to KIR3DL1 while HLA-B46 and Cw12 carry the C1 ligand that binds to KIR2DL2 and 2DL3." (PMID 27490240, 2016).
abdominal aortic aneurysm (1 paper, 2023). Enlargement and ballooning of the vessel that supplies arterial blood to the abdomen, pelvis and legs. "KIR3DL1/DS1 and their HLA-class I ligands are associated with aneurysm formation in abdominal aortic aneurysms (AAA)." (PMID 36834577, 2023).